IL2 (interleukin 2)
Diseases named in the same sentence as IL2 in open-access papers (continued):
Sharing a sentence is not in itself a finding about the gene and the disease.
cancer (continued). "In addition, many investigators have shown that IL-2 can improve the immune effect of cancer vaccines by potentiating the effect of tumor-specific lymphocytes." (PMID 24565030, 2014). "IL-2 can be administered to patients whose cancers have progressed after other agents." (PMID 24855563, 2014). "Further studies are needed to test whether IL-2 is detrimental to cancer vaccines, given the lower immune response rate in patients who received it." (PMID 24565030, 2014). "The role of IL-2, IL-15, IL-12, IL-18, and IL-21 in human NK cell biology is reviewed in the following sections, with emphasis on newer findings, followed by translational studies in cancer patients." (PMID 25054077, 2014). "Therefore, we sought to optimize the culture conditions for reliable expansion of γδT cells by culturing zoledronate-stimulated PBMC from both healthy individuals and patients with cancer in the presence of IL-2 plus IL-15." (PMID 25101086, 2014). "We also wanted to characterize the survival of patients who received cancer treatment after IL-2." (PMID 24855563, 2014). "Another study examining 23 cancer patients undergoing therapy with interleukin-2 and lymphokine-activated killer cells demonstrated 3-fold elevations of C3a desArg concentrations by the 8th day of therapy with concentrations of C4a desArg also being elevated by the end of therapy." (PMID 24884532, 2014). "It will also be important to test the binding ability of the human NKG2D-Fc-IL2 to different human cancer cell lines, as well as characterize the functionality of the IL-2 component before considering the generation of a clinical grade reagent for clinical trials." (PMID 22509395, 2012). "Since the middle of 1990s, IFN-α and IL-2 have long been used separately or in combination in the treatment for malignancies, to evoke stronger antitumor immune response as immune modulators or to stimulate immune cells as growth factors, but the clinical antitumor outcomes were limited." (PMID 22722448, 2012). "Moreover, IFN-α and/or IL-2 has been used in the treatment for malignancies for decades via modulating immunity." (PMID 22722448, 2012). "The mechanism responsible for these observations has not previously been elucidated, but these clinical reports suggest that depletion of Tregs may enhance the ability of IL-2 to elicit an antitumor immune response in cancer patients." (PMID 22303460, 2012). "Traditional approaches to exploit innate immunity for cancer immunotherapy include the activation of endogenous effectors (mainly NK cells) with systemic administration of cytokines (IL-2, etc.)and the adoptive infusion of ex vivo expanded NK or lymphokine-activated killer (LAK) cells." (PMID 22319542, 2012). "In this respect we have previously shown that the presence of IL- 2 receptors on cancer cells could compete for the IL-2 present in situ depleting the concentration of this growth factor that is absolutely needed to activate cytotoxic cells." (PMID 22642942, 2012). "Tregs are also induced in cancer patients receiving high dose IL-2." (PMID 22303460, 2012). "The interleukin 2 (IL2) pathway is another pathway that we find perturbed by many cancers." (PMID 22536907, 2012). "Concerning the successful modulation of NK cells in vivo, the approach may also be significant for NK-mediated cancer therapy, apart from other conventional regimens (i.e., transfusion of autologous or allogeneic NK cells and even administration of IL-2)." (PMID 22722448, 2012). "IL-2, IL-7, IL-15 and IL-21, sharing a common receptor γ chain (c-γ), control T lymphocyte homeostasis and proliferation and play major roles in regulating cancer-immune system interactions." (PMID 21943235, 2011).
cancer (continued). "Therefore, low dose IL-2 administered in the outpatient setting has been previously used to enhance cancer patients' immune response to monoclonal antibodies with little toxicity." (PMID 21693061, 2011). "IL-2, IL-7, IL-15 and IL-21 are of particular interest in cancer immunotherapy." (PMID 21943235, 2011). "In late-stage cancer, the expression of IL-2 in CD4+ and CD8+ cells was also reduced." (PMID 21437225, 2010). "One explanation for the initially observed need for high doses of IL-2 in the treatment of cancer might have originated from the very short half-life of purified IL-2 after injection (3-5 min in mice)." (PMID 21059266, 2010). "Targeting NK cells by combining DNA vaccine and immune modulators such as adjuvants (TLR agonists) and/or cytokines (e.g. IL-2, IL-15 or IL-21) could also be an exciting option as recently proposed in cancer immunotherapy." (PMID 20090916, 2010). "Some cancer vaccine trials showed an increase of T regulatory cells which may be due to the progressive disease status or the use of certain cytokines, such as IL-2." (PMID 20109232, 2010). "IL-2 was one of the first cytokines to be applied to cancer therapy." (PMID 19175928, 2009). "Further studies are required to confirm the functional properties of the effector, or regulatory phenotypes, as the anti-cancer effect of IL-2 could be related to the correct balance between these two types of immune cells." (PMID 19935800, 2009). "The role of IL-2 in cancer cellanergy has been demonstrated." (PMID 19277104, 2008). "For this reason, IL-2 has been used to generate T cellsto treat cancer by cell transfer techniques." (PMID 19277104, 2008). "IL2 is known to inhibit proliferation and growth of various cancer cells, and thus a downregulation of a subunit of its receptor may be one additional mechanism whereby growth factors in general promote growth." (PMID 15846300, 2005). "Immunisation of SCID/hu-PBL mice with the fusion protein resulted in increased MUC1-specific cellular immunity suggesting that combined application of MUC1 peptide and IL2 may mediate an effective immunity against MUC1-positive cancer." (PMID 12966437, 2003). "A positive clinical response, showing a cytologic disappearance of cancer cells and decrease of effusion, was observed in nine of 11 (82%) patients treated with OK-432 alone and in all five patients treated with OK-432 plus IL-2." (PMID 14612896, 2003). "The use of a combination of IL-2 and IL-12 is supported by a number of studies indicating that cancer eradication is a complex process and might require recruitment of multiple cytokines or costimulatory molecules." (PMID 12771934, 2003). "In addition, peptide-specific CTLs from cancer patients proliferated well for a long time in culture with IL-2 alone and thus these expanded cells became available in use for a 51Cr-release assay, whereas those from healthy donors did not (unpublished data)." (PMID 12232766, 2002). "Subjects were also asked whether they would undertake an experimental therapy (interleukin-2) for any of three malignancies, or recommend such treatment to a spouse or relative." (PMID 1892772, 1991). "Although IL-15 shares the same signal-transducing receptor subunits (IL-2Rβ and the common γ chain) with interleukin-2 (IL-2), the two cytokines drive fundamentally different CD8+ T-cell fates, a distinction that underlies their markedly divergent therapeutic profiles in cancer immunotherapy." (PMID 42039157, 2026). "Furthermore, IL-2 is an emerging target to enhance the effectiveness of cancer immunotherapy." (PMID 40018706, 2025). "The results showed that after HLB-apt treatment, T cell activation markers (CD69, CD3E), interleukin (IL-2), and other cytokines in Jurkat cells were significantly overexpressed (P<0.05), indicating an increase in Jurkat cell killing ability against cancer cells." (PMID 40761795, 2025).
cancer (continued). "Collectively, these studies reveal that Y33 IC potently stimulates CD8+ T cell expansion, activation, and effector functions without eliciting toxicities typically associated with IL-2 treatment, rendering this molecule a promising candidate for cancer immunotherapy." (PMID 40789741, 2025). "Notably, clinical trials using engineered IL-2 variants designed to preferentially stimulate intermediate-affinity IL-2R (ie, CD25-blocking agonists) have yielded disappointing outcomes in patients with cancer." (PMID 40789741, 2025). "Considering that IL-2 toxicity has limited widespread application in clinical trials, NKp30 upregulation, as shown here by the ectopic overexpression, may provide a novel modality to harness NK cells in cancer immunotherapy." (PMID 38698855, 2024). "However, the role of IL-2 in the regulation of activating receptors and the function of NK cells expanded for clinical trials is poorly understood and needs clarification for the full engagement of NK cells in cancer immunotherapy." (PMID 38698855, 2024). "Additionally, IL-2’s activation of regulatory T cells can counteract its anti-cancer effects." (PMID 38352877, 2024). "Furthermore, IL-2 deprivation-mediated NK cell dysfunction was overcome by NKp30 overexpression, proposing NKp30 upregulation as a viable modality to harness NK cells in cancer immunotherapy." (PMID 38698855, 2024). "PGE2 may therefore affect the response of TILs to IL-2, which is a notable finding given the current development of new classes of IL-2 receptor (IL-2R) agonists for cancer therapy and the emerging role of IL-2 signalling for productive anticancer responses by TCF1+ TILs33,34." (PMID 38658748, 2024). "Additionally, combining IL-2 therapy with PD-1 blockade can enhance T cells response to cancer." (PMID 39218982, 2024). "IL-2-based immunotherapies have shown great potential in cancer treatment, with several strategies currently in development to achieve immunostimulation without activating suppressive Tregs, including IL-2 muteins, PEGylated IL-2, IL-2/anti-IL-2 Ab complex, and IL-2-CD25 fusion proteins." (PMID 39595576, 2024). "To determine whether intracellular IL-15 also requires IL-15Rα to function, we used anti-IL-15 antibodies to immunoprecipitate cancer cell-intrinsic IL-15 and found that IL-15 was associated with IL-15Rα but not with the IL-2/IL-15Rβ or IL-2Rγ chains." (PMID 38637902, 2024). "One could also speculate that, if IL-2 and/or IL-15 exogenous administration is able to recover the absolute lymphocyte counts after radiation therapy, these treatments could have a double beneficial effect in cancer patients." (PMID 39315059, 2024). "The decrease in type 1 cytokines (e.g., IL-2, IL-12p70, and IFN-γ) may lead to decreased cell-mediated immunity, which together with a decrease in pro-inflammatory cytokines (e.g., IL-8) may result in increased risk of infection and cancer." (PMID 38255676, 2023). "Therefore, a variety of methods have been developed to prolong the half-life and weaken the limitations of the treatment window, while harnessing the immunostimulatory effects and overcoming unfavorable Treg toxicity of IL-2 for patients suffering from malignant tumors." (PMID 36936961, 2023). "Additionally, we aimed to analyze whether the CU06-1004 and IL-2 combination group could maintain or enhance the anti-cancer effect of IL-2 while inhibiting VLS." (PMID 37711172, 2023). "In addition, IL-2 and IL-2R are involved in several cancer-related pathways." (PMID 37516849, 2023). "Indeed, in patients with a persistent or heavy disease burden, T cells are often identifiable with tetramers, but not through stimulation assays that measure interferon-gamma (IFN-γ) or interleukin-2 (IL-2) secretion as a means of detecting the presence of cancer-specific T cells." (PMID 37287968, 2023). "A key function of IL-2 is activating the immune system, which could potentially eradicate cancer." (PMID 36874011, 2023).
cancer (continued). "The combination of screening IL-2 mutants for superior interaction with the β- and γ-subunit of the IL-2 receptor and developments of chimeric proteins by fusion of the cytokine to proteins like albumin or IgG for half-life extension, already led to promising results in cancer studies." (PMID 36562079, 2023). "In a study of patients with advanced-stage cancers, supplementation with Ganopoly, the polysaccharides fractions extracted from G. lucidum, for 12 weeks resulted in significant enhancement of cellular immunity (elevated IL2, IL6 and interferon γ in 80% of patients." (PMID 36497414, 2022). "For instance, the significant increases of IFN-γ and IL-2 seen after FSS treatment could be beneficial because IFN-γ is known to induce apoptosis in cancer cells, and IL-2 is known to increase persistence of chimeric antigen receptor (CAR) T cells after reinfusion." (PMID 35260156, 2022). "Furthermore, DN T cells, by restricting the availability of IL-2 in the cancer microenvironment, may prevent the NKs from proliferating, secreting IFN-g, and enhancing missed self-recognition." (PMID 35692772, 2022). "Indeed, only IFN-α and IL-2 are currently approved for treatment of cancer." (PMID 35529882, 2022). "Treatment of mice with recombinant preparations of the cytokine mimetic led to an increased CD8+: Treg ratio and improved therapeutic effects compared to murine IL2 in mouse cancer models, suggesting that the new cytokine may be more suitable for pharmaceutical applications." (PMID 33216834, 2020). "Thus, IL-2 was the first approved immunological treatment for cancer." (PMID 33027905, 2020). "Furthermore, we could show that the enhanced cytotoxicity of IL-2/IL-15-expanded cells extended to other cancer cell lines, also of different origin." (PMID 32983105, 2020). "Efficacy was observed with IL-15 in multiple murine immunotherapy trials including the syngeneic TRAMP (transgene adenocarcinoma mouse prostate) -C2 prostatic cancer, Pme1-1, B16 melanoma, MC38 and CT26 colon carcinoma models suggesting that IL-15 might be more effective than IL-2 in cancer therapy." (PMID 32508818, 2020). "Interestingly, this score significantly correlated with many cancer hallmarks associated with immune response, including TNF-α signaling via NF-κB, IL2, and STAT5 signaling; IL6, JAK, and STAT3 signaling; inflammatory responses; IFNα response; and IFNγ response." (PMID 32988398, 2020). "These phase I/0 clinical assays showed a satisfactory feasibility of this approach, with a reduced toxicity (mainly due to IL-2) and excellent Vγ9Vδ2 T cell expansion rates, but modest clinical efficacies, that might have been complicated by the bad clinical condition of cancer patients." (PMID 32528477, 2020). "Furthermore, IL2 can also promote the expansion of NKT-cells in cancer patients." (PMID 32582698, 2020). "However, IL-2 was the first cytokines to be successfully used in the treatment of cancer." (PMID 29854806, 2018). "Multiple other recombinant cytokines have already been approved for treatment of patients; IL-2 for cancer, several IFNα derivatives for cancer and viral infections, IL-11 thrombocytopenia induced by chemotherapy, IFNβ for multiple sclerosis and IFNγ for osteoporosis and cancer." (PMID 30622524, 2018). "Likewise, whether similar rules of progressive terminal differentiation with increasing IL-2 signals are also active in situations of chronic antigen stimulation—as occurs during persistent viral infections and cancers—remains to be defined." (PMID 30619342, 2018).
cancer (continued). "Alternatively—owing to its ability to induce proliferation and effector differentiation–strong and sustained IL-2 signals might be employed for immunotherapeutic interventions against cancers and chronic infections that rely on activation of a large pool of antigen-specific CD8 T cells." (PMID 30619342, 2018). "Therefore, the current study was performed to assess whether the concentration of ketamine, as adjuvant analgesics for patients with refractory cancer pain, was related to its effect on T cells IL-2/IFN-γ expression in vitro." (PMID 28422864, 2017). "However, whether combined administration of GM‐CSF and IL‐2 could produce specific immune responses to cancer stem cells (CSCs) was uncertain." (PMID 28205361, 2017). "For instance, the super-induction of IL-2 (and potential activation of natural killer cells) and stimulatory effects on bone marrow generation by activation of IL-3 and GM-CSF synthesis could be important in immune-compromised cancer patients." (PMID 29112154, 2017). "Moreover, the super-induction of IL-2 synthesis could be relevant in immunocompromised cancer patients that might need some form of external assistance for regulation of cell proliferation." (PMID 29112154, 2017). "Moreover, IL-2 is essential for the development and maintenance of Tregs that may represent a limitation for its use in patients with cancer." (PMID 28824651, 2017). "An older randomized trial with 30 cancer patients found out that supplementation of l-carnitine (1 g/day) may be used successfully to prevent cardiac complications during interleukin-2 (IL-2) immunotherapy in cancer patients with clinically relevant cardiac disorders." (PMID 26985904, 2016). "Similarly, systemic administration of IL-2 as the treatment for cancer should take into consideration the age of the patient, since aging might diminish MSCs similar to what is seen for their ex-vivo replicative aging." (PMID 26255627, 2015). "Although the mechanisms of T-cell tolerance induced in chronic infection and cancer may differ from those involved in tolerance to self-antigen, the impaired proliferation and production of IL-2 in response to antigen stimulation are hallmarks of all tolerant T cells." (PMID 24987395, 2014). "Thus, searching for novel immunomodulator which can work synergistically with IL-2 to reduce or replace its working dosage has been proposed from time to time and this may contribute to the success of adoptive immunotherapy in cancer treatment." (PMID 23800124, 2013). "We recommend that dendritic cells used in immunotherapy for cancer (or infectious diseases) be routinely screened for IL-2-producing DCs because inadvertent delivery of IL-2-producing DCs may undermine the effectiveness of DC-based therapy by promoting Treg suppressor function." (PMID 22984435, 2012). "However, minimal activity of IL-2 in the treatment of other cancers has been observed." (PMID 19175928, 2009). "Nitric oxide (NO), a biologically active mediator generated in many cell types by the enzyme NO synthase, may play an important role in cardiovascular toxicity that is frequently observed in cancer patients during intravenous (i.v.)interleukin 2 (IL-2) therapy." (PMID 8883421, 1996). "In both TILs and blood lymphocytes, the Tac antigen was consistently present on greater numbers of CD4+ T lymphocytes than on the CD8+ T lymphocytes (P less than 0.001) and as this is a component of the interleukin 2 (IL-2) receptor this may be of relevance to the use of IL-2 in TIL cancer therapy." (PMID 2124138, 1990). "Due to its role in promoting T cell proliferation, IL-2 is often referred to as “T-cell growth factor” (TCGF), which supports its application in cancer immunotherapy." (PMID 40869161, 2025). "Cytokine antibody array analysis revealed that MMP28 knockdown suppressed the production and release of IL-2, IL-5, IL-8, MCP-1, and VEGFA by cancer cells." (PMID 39972459, 2025).